SMR3A (submaxillary gland androgen regulated protein 3A)
Description:
May play a role in protection or detoxification.
Synonyms: PBI; PROL5; PRL5; P-B1
Tractability: Antibody: UniProt places it where antibodies can reach, with high confidence; its Gene Ontology location is reachable by antibodies, with high confidence; UniProt predicts a signal peptide or a membrane-spanning region.
Gene: Protein-coding gene on chromosome 4 (70,360,760 to 70,367,158, forward strand). Ensembl gene ENSG00000109208.
Subcellular location: Secreted
Gene Ontology:
Molecular function: protein binding; endopeptidase inhibitor activity
Biological process: regulation of sensory perception of pain
Cellular component: extracellular region
Genetic constraint (gnomAD): Loss-of-function variants: 0 observed, 1.2 expected, observed/expected ratio (o/e) 0, 90% interval 0 to 1.66. That is too few expected variants to judge how well the gene tolerates losing a copy. Missense variants: 182 observed, 169.04 expected, observed/expected ratio (o/e) 1.08, 90% interval 0.95 to 1.22. Synonymous variants: 48 observed, 59.78 expected, observed/expected ratio (o/e) 0.8, 90% interval 0.64 to 1.02.
Homologues: Orthologues: chimpanzee SMR3A (96% identical), macaque SMR3A (84% identical).
Diseases named in the same sentence as SMR3A in open-access papers:
SMR3A is named in the same sentence as 4 diseases in open-access papers, as found by Europe PMC text mining. Sharing a sentence is not in itself a finding about the gene and the disease. The quoted sentences say what the papers report.
gastric cancer (1 paper, 2022). A primary or metastatic malignant neoplasm involving the stomach. "Co-expression genes are involved in the development of multiple cancers, for example, high expression of SMR3A suggests poor prognosis in patients with head and neck squamous cell carcinoma, and WNT7B promotes gastric cancer progression and metastasis." (PMID 35350563, 2022).
oropharyngeal squamous cell carcinoma (1 paper, 2017). "More recently, SMR3A expression was detected in a subgroup of patients with primary oropharyngeal squamous cell carcinoma (OPSCC) and served as an independent risk factor for unfavorable prognosis." (PMID 28166815, 2017). "In line with this assumption, ESR2-positive oropharyngeal squamous cell carcinoma (OPSCC) with high SMR3A expression had an unfavorable progression-free and disease-specific survival as compared to those tumors with low SMR3A expression." (PMID 28166815, 2017).
tumor (2 papers, 2017 to 2018). "Radioresistant tumor cells were also positive for submaxillary gland androgen-regulated protein 3A (SMR3A), which is a putative ERβ downstream target and was shown to serve as a prognostic biomarker for HNSCC patients." (PMID 29498642, 2018). "So far, experimental data support a model in which ESR2 and SMR3A co-expression after fractionated IR is a characteristic feature for a subpopulation of treatment resistant tumor cells." (PMID 28166815, 2017). "Fractionated irradiation (IR) revealed an accumulation of tumor cells with prominent SMR3A expression, which was accompanied by an up-regulation of the estrogen receptor 2 (ESR2)." (PMID 28166815, 2017). "FaDu cells were selected to generate stable clones (FaDu-SMR3A) with ectopic SMR3A expression in order to address its impact on tumor-relevant processes in vitro." (PMID 28166815, 2017). "In the current study, we demonstrate prominent SMR3A expression in tumor cells upon fractionated irradiation (IR) and provide experimental evidence that induced SMR3A expression serves as a surrogate maker for active estrogen receptor 2 (ESR2) signaling in radioresistant tumor cells." (PMID 28166815, 2017). "In this study, we unraveled prominent SMR3A expression in vital tumor cells upon fractionated IR." (PMID 28166815, 2017). "In summary, these data suggested that SMR3A expression serves as a potential surrogate marker for active ESR2 signaling in a subpopulation of radioresistant tumor cells, raising the question, whether pharmacological interference sensitizes these cells to fractionated IR." (PMID 28166815, 2017). "Positive staining for ESR2 (ESR2pos) in tumor cells was detected in 65.1% of tumors and a high staining pattern correlated significantly with a higher SMR3A immunoreactivity score as compared to samples without detectable ESR2 staining (p = 0.044)." (PMID 28166815, 2017). "However, we did not observe any significant difference in tumor cell proliferation or migration between FaDu-SMR3A clones and mock controls." (PMID 28166815, 2017). "In summary, these data suggested that SMR3A has no major impact on tumor cell physiology under normal growth conditions but raised the attractive question, whether it serves as a marker for a distinct subpopulation of tumor cells with higher resistance against well-established treatment options." (PMID 28166815, 2017).
SMR3A also shares sentences with these, for which no sentence is quoted: head and neck squamous cell carcinoma (1 paper).